IL6 (interleukin 6)
Diseases named in the same sentence as IL6 in open-access papers (continued):
Sharing a sentence is not in itself a finding about the gene and the disease.
lupus (continued). "The literature lacks studies, with a clinical perspective, on the relationship between IL-6 serum levels and the characteristics of the disease in patients with systemic lupus erythematosus (SLE)." (PMID 37762312, 2023). "Furthermore, in SLE murine model, IL-6 deficient mice had a delayed onset of lupus nephritis, enhanced kidney function, and a longer lifespan." (PMID 37343193, 2023). "Of interest, pathways associated with systemic lupus erythematosus (SLE), Th1 responses, IL-6 signaling, and neuroinflammation were among those pathways increased in AMS SLCLs compared to HC SLCLs." (PMID 36778367, 2023). "Precisely modulating IL-6-expressing neutrophils in the kidney would be a potential therapeutic strategy to improve clinical treatment for lupus." (PMID 37273451, 2023). "Among which, IL-6 derived from neutrophil (Ly6g) “rise” to be the major signal interacting with B cells in the lupus kidney." (PMID 37273451, 2023). "Monocytes are the primary source of the T helper 2 (Th2) cytokines IL-6 and IL-10 in the peripheral blood, which are elevated in lupus patients." (PMID 37198993, 2023). "Seluang fish oil treated lupus patients presented with decreased IL-1, IL-6, and IL-17 levels compared to the placebo group." (PMID 35431950, 2022). "Typically, pCRP levels remain low or only slightly elevated in SLE flares even if IL-6 is elevated, and these levels are often higher during infections than lupus flares." (PMID 35690780, 2022). "Not surprisingly, studies in patients and lupus mice also exhibit an increasing baseline of TNF-α and IL-6 compared to healthy volunteers, which correlates with lupus disease severity." (PMID 35897790, 2022). "We observed that TLR7 or TLR9 agonists induce higher amounts of MCP-1 and IL-6 on PMs from lupus-prone mice than control mice, confirming that PMs from diseased mice present a more pro-inflammatory phenotype." (PMID 35211864, 2022). "John’s wort) proved effective in significantly reducing the serum level of IFN-g, IL-17A, IL-1b, TNF-a, and IL-6 in lupus-prone mice." (PMID 35431950, 2022). "Our study is consistent with those from others showing that lower IL-6 contributes to improvements in proteinuria and survival in lupus mouse models." (PMID 36510250, 2022). "Other studies have shown that basophils promote type 17 immune responses by producing IL-6 and that chronic depletion of basophils exacerbates the lupus phenotype in MRL-lpr/lpr mice and the severity of EAE in WT mice." (PMID 34747366, 2021). "Although the importance of IL-6 in the pathogenesis of lupus has been well documented, pharmacological targeting of IL-6 has not been successful." (PMID 34394075, 2021). "Marques and colleagues, for example, showed a stronger positive expression of IL-6 in mucosal biopsies of lupus patients compared to the specimens of normal controls." (PMID 34975831, 2021). "Blood cytokines reflect elicitation of autoimmunity and disease severity in systemic autoimmune diseases, such as interleukin 6 (IL-6) and IL-10 in systemic lupus erythematosus." (PMID 34539561, 2021). "Lupus induced an increase in the levels of pro-inflammatory cytokine IL-6 while decreasing the anti-inflammatory cytokine TGF-β1 levels compared with healthy mice." (PMID 34394075, 2021). "Unsurprisingly, our results revealed that IL-6 and IL-1β cytokine levels in the hippocampus of lupus mice were significantly higher than those in the control mice, with albumin accumulation in situ (data not shown)." (PMID 34645459, 2021). "The functional role of interleukin-6 (IL-6) in systemic lupus erythematosus (SLE) is uncertain and in need of clarification." (PMID 34975831, 2021). "In support of this idea, we found that lupus-established sanroque mice overexpress GM-CSF, IL-6, and IFN-γ in their spleens, and CD4+ T cells are in part responsible for their production." (PMID 33643317, 2021).
lupus (continued). "B cell–derived IL-6 has been shown to be necessary for the development of spontaneous GCs in a mouse model of lupus and has also been suggested to be important in the development of experimental autoimmune encephalomyelitis." (PMID 34197340, 2021). "The IL-6 and IL-17A levels were significantly higher in the lupus group compared with the adjuvant and control groups." (PMID 34824318, 2021). "Serum levels of lupus-related pro-inflammatory cytokines including IL-6, BAFF, and IL-17 were markedly decreased by baricitinib treatment." (PMID 34497607, 2021). "IL-6 and IL-21 are pro-inflammatory cytokine for lupus progression, and also important regulators of TFH cell generation." (PMID 33632240, 2021). "More research will be needed to understand the complex immune regulation of cytokines by IL-6 and IL-6 trans-signaling in systemic lupus erythematosus and its effects on different organ manifestations." (PMID 33669022, 2021). "In contrast, the correlation of serum IL-6 level with SLE activity was significant when active disease was defined as Systemic Lupus Erythematosus Disease Activity Index (SLEDAI)>4." (PMID 33084768, 2020). "In lupus keratinocytes, elevated IFNs promote IL-6 production following TLR or UVB stimulation of keratinocytes and also promote photosensitive responses and disruption of the epidermal barrier." (PMID 32644977, 2020). "It is interesting to note that monocytes from systemic lupus erythematosus have defects in adhesion and produce elevated levels of IL-6, TNF-a, and IL-10 than healthy monocytes." (PMID 32645059, 2020). "Though not all changes were statistically significant, similar observations were made for TNF-α, IL-1α, IL-6, and IL-18, which are known for their roles in inflammation and lupus development." (PMID 32413078, 2020). "The results showed that plasma levels of TNF‐α, IL‐1β, IL‐6 and IL‐23 were significantly up‐regulated in pristane‐induced lupus mice compared with those in the control group." (PMID 33079487, 2020). "The predominant systemic inflammation (serum IL-6) in lupus mice over WT is possibly due to the inhibitory signalling defect and hyper immune-responsiveness of FcGRIIb−/−3 and pristane mice, respectively." (PMID 31964918, 2020). "Numerous studies have explored serum IL-6 levels in systemic lupus erythematosus (SLE) and their correlation with disease activity." (PMID 33084768, 2020). "Further, in addition to IFNα, pristane induces production of numerous NFκB-induced cytokines, including IL-6, IL-1b, and TNFα, which contribute to other manifestations of lupus." (PMID 33101313, 2020). "A study on systemic lupus erythematosus showed that miR-410 downregulates IL6 and IL10 expression, and its overexpression significantly reduced the expression levels of TGF-b1 in SV40MES13 cells." (PMID 33005638, 2020). "Reduced lupus disease manifestations were seen, as well, in BXSB/MpJ and MRL-lpr lupus-prone mice, together with a reduced expression of the proinflammatory cytokines IL-6, IL-12, and TNF-α." (PMID 31137916, 2019). "In conclusion, our studies showed that anti-pneumococcal vaccination with Prevnar-13 associates with amelioration of disease severity in murine lupus, a phenomenon associated with reduced TNF-α and IL-6 production by B cells and increased TFR/TFH ratio." (PMID 31824490, 2019). "The inflammatory cytokine IL-6 supports long-lived plasma cell survival in vitro and is increased in the serum of patients with lupus." (PMID 31770269, 2019). "There is compelling evidence that blockades of cytokines, including BAFF, BCMA, APRIL, IL-6, and/or IL-21, inhibit B cell proliferation in murine lupus." (PMID 31795353, 2019). "Neat1 expression is increased in Systemic Lupus Erythematosus and knockdown of Neat1 reduces cytokines such as IL-6 and CXCL1038." (PMID 31673072, 2019).
lupus (continued). "A previous study also reported B-cells, T-cells, and secretion of pro-inflammatory cytokines including tumour necrosis factor α and interleukin 6 contribute to glomerular lesions in lupus-prone mice." (PMID 29980767, 2018). "This difference is driven by increased production of type I IFNs, as control keratinocytes treated with type I IFNs increase their IL-6 production, while lupus keratinocytes treated with type I IFN blockade have decreased IL-6 production." (PMID 30405625, 2018). "This study also shows that an increased proinflammatory cytokine, IL-6 from the BLIMP1-deficient DCs facilitates Tfh differentiation as haplosufficiency for IL-6, prevents lupus-related phenotypes including Tfh cells." (PMID 30123218, 2018). "IL-6 administration to lupus-prone mice increases autoantibody production and accelerates the progression of glomerulonephritis." (PMID 30547812, 2018). "Among many pro-inflammatory cytokines produced by activated APC and T cells, IL-6 is known to promote antibody production from B cells and suppress Treg cells, which are important for lupus progression in lpr mice." (PMID 28697806, 2017). "Studies targeting IL-6 in mouse models of lupus have shown significant effects resulting in reduced serum autoantibody levels and diminished renal pathology." (PMID 29430334, 2017). "Intriguingly, decreased IL-6 hypomethylation has been deemed as an active regulator in lupus patients with kidney damage." (PMID 28785369, 2017). "CD69 expression on MAIT cells in patients with lupus positively correlated with plasma concentrations of IL-6, IL-18, and IFN-α." (PMID 28288675, 2017). "It has been previously shown that an Il-6 knock-out mouse completely abrogates lupus phenotypes in B6.Sle1." (PMID 27228057, 2016). "Abnormal production of inflammatory cytokines such as IFNγ, IL-1β, IL-6, and TNFα is a key characteristic of lupus." (PMID 27070142, 2016). "Contradictory to these observations, however, one study showed that BMDC from several lupus-prone mouse models, when activated by LPS, possessed reduced IL-6-producing ability compared to BMDC from B6 mice." (PMID 27034965, 2016). "It has been shown in the lupus mouse model that introduction of TSA (a broad spectrum HDAC inhibitor) reduced IL-6 level and proteinuria." (PMID 27594771, 2016). "Possible contributions of IL6 to disease in human SLE and in mouse models of lupus were first suggested by the identification of elevated levels of IL6 levels in sera of patients with SLE." (PMID 27050763, 2016). "The lupus mice exhibited a significant elevation in plasma levels of IL-4, IL-6, IL-7, IL-12, IL-17, IFN-α, IFN-γ, TGF-β, BAFF and APRIL and a marked elevation of IgG2a, IgG3 and ant-dsDNA autoantibodies compared with normal healthy mice." (PMID 25909640, 2015). "Increased production of tumor necrosis factor α, interleukin (IL)-1, IL-6, and other pro-inflammatory cytokines has been reported in patients with SSc and systemic lupus erythematosus who have calcinosis." (PMID 26134593, 2015). "Higher levels of serum IL-6 were found in lupus patients in this study, and African American women had the highest level when compared to European American women and males." (PMID 26583155, 2015). "Lupus patients, particularly African Americans, had significantly higher levels of IL-6 (p = 0.0001) and TNF-α (p = 0.042)." (PMID 26583155, 2015). "This study showed that, in a subgroup of women on DHEA therapy, those lupus patients with the TT genotype had lower levels of IL-6 expression compared to those patients on DHEA therapy with GG or GT genotypes." (PMID 26583155, 2015). "Our data showed higher levels of IL-6 expression in lupus patients (p = 0.0001) and that African American women with lupus had higher levels than European American women (p = 0.0272)." (PMID 26583155, 2015).
lupus (continued). "We observed that lupus mice had aberrant and significantly elevated levels of IL-4, IL-6, IL-7, IL-12, IL-17, IFN-α, IFN-γ, TGF-β, BAFF and APRIL compared with the control non-lupus healthy mice (* P < 0.05)." (PMID 25909640, 2015). "MZ B cells from lupus-prone B6.TC mice produce more IL6 than WT mice whereas levels of MZ B cell-derived IL10 remain comparable." (PMID 26068236, 2015). "Overall, these results demonstrate that the dysregulation of cytokine networks in DCs from lupus mice, in which IL-6 and both type I and II IFNs play a major role, contribute to the activation of pathogenic B cells." (PMID 25093822, 2014). "Blocking IL-6 signaling in murine models of lupus ameliorated disease and suppressed the production of anti-dsDNA autoAbs." (PMID 25093822, 2014). "To further understand if the IL-6 down-regulation in the presence of IL-10 is impaired in the B cells from lupus-prone TC mice, we measured the cytokine levels in the culture supernatants." (PMID 25093822, 2014). "Inhibition of IL-6 by tocilizumab has shown promising responses in clinical and serologic manifestations of lupus activity in patients with SLE." (PMID 23986016, 2014). "Monotherapy of systemic lupus erythematosus (SLE) patients with chloroquine results in a decrease in serum levels of IL-6, IL-18, and TNF-α." (PMID 25348033, 2014). "Our results show that anti-CD40 activated BMDCs from TC lupus-prone mice induce a greater B cell proliferation in an IL-6 and IFN-γ dependent manner." (PMID 25093822, 2014). "This indicates that the TC lupus-prone B cells are less responsive to anti-inflammatory conditions, resulting in the inefficient down-regulation of the inflammatory cytokine IL-6." (PMID 25093822, 2014). "For example, treatment with anti-IL-6 or anti-IL-6 receptor antibody results in reduced severity of kidney damage in lupus-prone mice whereas recombinant IL-6 exacerbates glomerulonephritis." (PMID 23557436, 2013). "Treatment of lupus prone mice with an IL-6 monoclonal antibody decreases anti-dsDNA titres and proteinuria and reduces mortality." (PMID 23642011, 2013). "In systemic lupus erythematosus, the elevated levels of Hsp90 in PBMCs were correlated with increased levels of circulating IL-6." (PMID 23936217, 2013). "Complete deficiency of IL-6 in MRL-Faslpr mice reduces clinical, immunological and histological indices of lupus and improves survival." (PMID 23557436, 2013). "Murine lupus models indicate the involvement of IL-6 in B-cell hyperactivation and the onset of SLE." (PMID 23702100, 2013). "It was also found that increased plasma levels of IL6, IL8 and MCP-1 were associated with cardiovascular risk in patients with systemic lupus erythematosus." (PMID 22883023, 2012). "IL-6 production in lupus is reported to mediate by immune complexes that transmit signals through TLR7 and 9 and Fcγ receptor." (PMID 23140401, 2012). "Lupus serum contains immune complexes and is able to induce the production of IL-6 and IL-10 from PBMCs." (PMID 23140401, 2012). "We found increased levels of IL-6 in plasma of lupus patients compared with those in healthy controls (16.03 ± 20.03 pg/ml versus 6.29 ± 4.09 pg/ml; P = 0.040)." (PMID 20334681, 2010). "An intraperitoneal administration of an anti-IL-6 MAB suppressed the production of anti-ds DNA Abs in models of murine lupus and prevented the development of severe kidney disease." (PMID 27713252, 2010). "CD40L treatment of bone-marrow-derived DCs from lupus-prone B6.TC mice induced higher production of IL-6, IL-10, and TNF-α than in B6 mice." (PMID 18718031, 2008). "Treatment with quercetin in murine lupus models was associated with kidney protection through the downregulation of inflammatory markers (TGF-β1, TNF-α, Bcl-2-associated protein x (Bax), IL-6) and counts of senescent T cell and follicular helper T cell subsets." (PMID 40852730, 2025).
lupus (continued). "First, developing precision risk stratification tools requires integrating AID-specific parameters such as disease activity metrics (e.g., SLEDAI for lupus), CNS-penetrating autoantibody profiles, and dynamic inflammatory trajectories like IL-6 kinetics to predict individual vulnerability." (PMID 41322215, 2025). "Moreover, UVB and TLR stimulation of keratinocytes from lupus patients led to increased IL-6 production, further amplified by Type I interferons." (PMID 41008557, 2025). "This reinforces the hypothesis that specific gut microbes exacerbate lupus by promoting pro-inflammatory Th17 pathways, increasing IL-6 production, and interfering with Treg function." (PMID 39940777, 2025). "Considering the effect of drug treatment, hydroxychloroquine (HCQ), known for its anti-inflammatory properties, significantly reduced IL-6 levels, an effect already observed in patients affected by systemic lupus erythematosus (SLE), a chronic autoimmune disease." (PMID 39061002, 2024). "Besides, the expression of lupus-related pro-inflammatory factors, including Il6, Gzmb, and Ifna, decreased with 2D4 treatment, the expression of Tnfb was also reduced." (PMID 39551768, 2024). "While such experiments represent possible future directions in firming the causality of IL-6 in NPSLE-like disease, the behavioral findings in IL-6 KO lupus mice from the present study represent valuable first steps in dissecting this potential etiology of NPSLE." (PMID 38600510, 2024). "Additionally, neutrophils in lupus-afflicted kidneys supplied IL-6 via SLC7A11 to boost B cell resistance against ferroptosis; suppressing SLC7A11 markedly heightened B cell ferroptosis while reducing B cell proliferation." (PMID 38965216, 2024). "Importantly, expression of pro-inflammatory cytokines (IL-1β, IL-6, TNFα and IFNγ) was increased in PVAT from lupus mice, concomitant with elevated plasma levels of TNFα, IFNγ and IL-6." (PMID 37006244, 2023). "Biopsy samples from DLE and SCLE skin lesions also showed significantly upregulated IL-6 expression, and keratinocytes from the unaffected skin of lupus patients produced significantly more IL-6 than those from healthy control subjects after treatment with TLR2, 3, or 4 agonists or UVB radiation." (PMID 36769633, 2023). "Therefore, paying attention to the cytokine microenvironment and immunological context present in lupus (high levels of IL-6 and TNF-α) can probably partially justify the results observed in this study." (PMID 38072921, 2023). "By contrast, BV2 cells treated with TNF-α in the presence of NF-κB inhibitor pyrrolidine dithiocarbamate (PDTC) suppressed the expression of CD68 and IL-6 and activity of NF-κB, implying that TNFα controls microglial activation by NF-κB signaling in lupus with depression." (PMID 38164134, 2023). "Moreover, studies with azithromycin and monocytes from systemic lupus erythematosus patients revealed that the PI3K signalling pathway is involved in the regulation of cytokine secretion (IL-6, IL-1β, IL-10)." (PMID 35742807, 2022). "To determine whether miR-183C miRNAs play a role in regulating lupus-related inflammatory cytokines such as IFNγ and IL-6, we inhibited miR-182 alone or miR-183C miRNAs with specific antagomirs in vitro in splenocytes." (PMID 35873462, 2022). "Indeed, induced gut leakage in a mouse model of lupus enhanced disease characteristics, including the production of anti-dsDNA antibody, serum IL-6 as well as cell apoptosis." (PMID 35795671, 2022). "This study reports that in vitro inhibition of miR-182 alone or miR-183C by specific antagomirs in activated splenocytes from autoimmune-prone MRL/lpr and control MRL mice significantly reduced lupus-related inflammatory cytokines, interferon-gamma (IFNγ), and IL-6 production." (PMID 35873462, 2022).